ALB (albumin)
Diseases named in the same sentence as ALB in open-access papers (continued):
Sharing a sentence is not in itself a finding about the gene and the disease.
metabolic acidosis (27 papers, 2014 to 2025). "The ACAG demonstrates enhanced diagnostic accuracy in identifying metabolic acidosis in patients diagnosed with hypoproteinemia, as it explains the influence of diminished serum albumin concentrations on the anion gap." (PMID 41401154, 2025). "The use of i.v. bicarbonate in patients with metabolic acidosis is controversial due to the concern of displacing hydrogen ions from albumin, thus freeing up binding spots on albumin for Ca2+ and lowering ionized Ca2+." (PMID 37016309, 2023). "In the subgroup analysis based on the reasons for using CRRT, albumin was found to have a protective effect on the prognosis of patients with volume overload and metabolic acidosis." (PMID 34496793, 2021). "In patients with metabolic acidosis, the risks of 28-day and 90-day mortality decreased with the increasing albumin, and the adjusted HR (95% CI) was 0.24 (95% CI 0.11–0.51, p < 0.001) and 0.28 (95% CI 0.15–0.53, p < 0.001), respectively." (PMID 34496793, 2021). "In case of metabolic acidosis, is the plasma anion gap corrected for albumin better than the uncorrected plasma anion gap in differentiating acid excess from base deficit?" (PMID 31418093, 2019). "The majority (23 of 31) of patients with RTA presented with RTA type II, while 8 of 31 patients showed characteristics of RTA type I. However, in 26 of the 31 patients with RTA, metabolic acidosis was neutralized mainly by simultaneously decreased plasma albumin leading to a neutral arterial pH." (PMID 25888397, 2015). "Additionally, there is a reduction in food intake and an increase in gastrointestinal disorders; an uncontrolled hydric balance; an anaerobic activity which can increase serum levels of lactate; metabolic acidosis; and reduction in the levels of ferritin and albumin." (PMID 33557771, 2021). "This suggests that metabolic acidosis in AKI results not only from an increase in unmeasured anions containing non-volatile acids but also from factors such as phosphate and albumin." (PMID 40502910, 2025). "On the surface, ACAG is an organic combination of albumin and AG thatcan more comprehensively reflect the true level of acid-base in the body.However, in clinical practice, ACAG reflects the two pathological conditions ofhypoalbuminemia and metabolic acidosis." (PMID 39076311, 2024). "The AG/corrected AG could only be calculated in 78 patients with either a metabolic acidosis or mixed disorder (metabolic acidosis-respiratory acidosis/alkalosis) because the serum albumin concentrations were not measured in the remaining patients." (PMID 36060846, 2022).
pancreatic ductal adenocarcinoma (27 papers, 2010 to 2026). An infiltrating adenocarcinoma that arises from the epithelial cells of the pancreas. "Neoadjuvant chemotherapy withCombination of nanoparticle albumin (nab) associated paclitaxel with gemcitabine and folfirinox infusion for locally advanced and non‐metastatic pancreatic ductal adenocarcinoma." (PMID 39434498, 2025). "Emerging evidence indicates that an elevated C-reactive protein-to-albumin ratio (CAR) may be associated with a poor prognosis in pancreatic ductal adenocarcinoma (PDAC)." (PMID 33028394, 2020). "The NCCN (National Comprehensive Cancer Network) recommends that patients with advanced pancreatic ductal adenocarcinoma should receive a combination of folic acid and albumin paclitaxel + gemcitabine for 4–6 months, followed by radiotherapy." (PMID 38288098, 2023). "Collectively, our data revealed SOX8/EZH2/SPARC signaling induced primary chemo-resistance of albumin-bound paclitaxel in pancreatic ductal adenocarcinoma." (PMID 35173526, 2022). "Nab‐paclitaxel (Abraxane), which is a nanoparticle form of albumin‐bound paclitaxel, is one of the standard chemotherapies for pancreatic ductal adenocarcinoma (PDAC)." (PMID 35174623, 2022). "FcRn expression is known to increase the sensitivity of pancreatic ductal adenocarcinoma to albumin‐conjugated doxorubicin." (PMID 33497038, 2021). "In conclusion, we developed an accurate multivariable prognostic model for resectable pancreatic ductal adenocarcinomas, incorporating age, tumor differentiation and size, preoperative CA 19-9, serum albumin and alkaline phosphatase." (PMID 20508721, 2010). "PURPOSE: This study aimed to investigate the prognostic impact of preoperative indicators that reflect systemic inflammatory, nutritional, and immune status, focusing on the C-reactive protein–albumin–lymphocyte (CALLY) index in patients undergoing surgery for pancreatic ductal adenocarcinoma." (PMID 41854738, 2026). "Nevertheless, the prognostic significance of combining lymphocytes, albumin, and neutrophils (LANR) in patients with pancreatic ductal adenocarcinoma (PDAC) undergoing radical resection has yet to be thoroughly examined." (PMID 38714979, 2024). "Pancreatic ductal adenocarcinoma (PDAC) is a highly aggressive tumor with a poor prognosis, despite the emergence of chemotherapies such as gemcitabine plus albumin-bound paclitaxel (nab-paclitaxel, AG), unmet medical needs still exist for patients with metastatic PDAC (mPDAC)." (PMID 40463875, 2025). "The majority of pancreatic ductal adenocarcinoma (PDAC) patients experience disease progression while on treatment with gemcitabine and nanoparticle albumin‐bound (nab)‐paclitaxel (GemPac) necessitating the need for a more effective treatment strategy for this refractory disease." (PMID 38131168, 2023). "Lei and coworkers, for instance, discussed the use of nanomedicine such as nanoparticle albumin-bound paclitaxel (nab-PTX), abraxane, or a liposomal formulation of irinotecan as effective improvements of anti-cancer drug delivery for pancreatic ductal adenocarcinoma." (PMID 33520715, 2020).
pulmonary tuberculosis (27 papers, 2011 to 2025). A bacterial infection that affects the lungs and is caused by Mycobacterium tuberculosis. "The findings demonstrated that pulmonary TB causes significant impairment of PF and that albumin, BMI < 18.5 kg/m2, lesion number ≥ 3, cardiovascular disease, male, and respiratory disease were associated with impairment of PF." (PMID 37076819, 2023). "Univariate logistic regression analysis found that BMI, pulmonary tuberculosis, operation time, operation blood loss, preoperative lymphocytes, preoperative serum albumin, preoperative CRP, and preoperative ESR are risk factors." (PMID 35571899, 2022). "We did not analyze other non-specific biomarkers of inflammatory response associated with severe pulmonary TB, such as C-reactive protein, albumin and globulin." (PMID 34276654, 2021). "In this study, the ratio of malnourished patients according to based on Albumin was lower than that of the author Le TT, and higher than the study on pulmonary tuberculosis patients in Brazil." (PMID 37304581, 2023). "According to the OR value, pulmonary tuberculosis (OR = 0.270) was assigned as 1-point, preoperative serum albumin (OR = 0.754) was assigned as 2 points, and operation time (OR = 1.017) was assigned as 3 points." (PMID 35571899, 2022). "As an alternative index of nutritional status of the body, albumin mostly decreased in pulmonary tuberculosis patients." (PMID 32029876, 2020). "It has been suggested that most of the elderly pulmonary TB patients have comorbid disorders and show deterioration of nutritional status represented by low serum albumin levels and decreased dietary intake." (PMID 30423855, 2018). "Higher levels of albumin have been considered as a predictor of a better outcome inpatients with pulmonary tuberculosis." (PMID 25029650, 2014). "A study of 30 patients with pulmonary TB in England revealed a reduction in BMI, triceps skin hold, arm muscle circumference and serum albumin." (PMID 23565890, 2013). "Regarding the implications for clinical practice, TRIAD-TB offers a pragmatic, bedside-ready way to identify pulmonary TB inpatients at the highest short-term risk using data every ward already collects (vitals, CBC-derived SII, CRP, BMI, albumin) and their 72 h trajectories." (PMID 41462913, 2025). "The nutritional status of pulmonary tuberculosis patients was assessed using BMI, MUAC, SGA, and Albumin." (PMID 37304581, 2023). "Although it demonstrated good calibration and predictive performance, its use requires albumin measurement—a test not routinely performed in the initial evaluation of suspected pulmonary tuberculosis, particularly in outpatient or resource-limited settings." (PMID 40601767, 2025). "In a prospective observational study of adults with smear-positive pulmonary tuberculosis in Sabah, Malaysia, we measured serial 25D, 1,25D, vitamin D-binding protein (VDBP), albumin, calcium, parathyroid hormone, chest x-ray, week 8 sputum smear/culture and end-of-treatment outcome." (PMID 28449659, 2017). "A risk prediction nomogram model for IGRA false-negative results in pulmonary tuberculosis patients was constructed using RBC, ALB, and NLR as predictors." (PMID 40601767, 2025). "Sato and colleagues reported that in cured patients with active pulmonary TB, serum vitamin D levels showed a significantly negative correlation with time duration until sputum conversion, as well as platelets count and CRP and a significant positive correlation with serum albumin." (PMID 38982373, 2024).
brain tumor (26 papers, 2011 to 2026). "In particular, as SPARC overexpression is associated with malignancy in brain tumor cells, the use of albumin could be expected to take advantage of the presence of SPARC to increase ICG accumulation in tumors." (PMID 36614294, 2023). "Typically, albumin is prevented from entering the brain, but in certain situations, such as the presence of a brain tumor, the absorption of albumin by tumor tissues increases." (PMID 41002483, 2025). "A study conducted in DIPG, an aggressive pediatric brain tumor, tested in vitro on tumor neurospheres the serum albumin coated passion-fruit-like nanoarchitectures (NAs-HSA) loaded with the chemotherapeutic agent doxorubicin." (PMID 36839827, 2023). "The properties and structure of serum albumin and its role in targeting brain tumors were presented." (PMID 37836018, 2023). "To evaluate, if systemically delivered SPNPs can home to brain tumors, SPNPs loaded with Alexa Fluor 647-labeled albumin were prepared." (PMID 33173024, 2020). "In an earlier study on elective neurosurgery brain tumour resection from our centre, albumin decreased Multiplate aggregation more than HES." (PMID 30202516, 2018). "Thirty-nine patients undergoing elective brain tumour surgery with craniotomy received either 130/0.42 hydroxyethyl starch or 5 % albumin infusions." (PMID 26425342, 2015). "Despite persisting challenges, including formulation consistency and clinical translation enhancement, functionalized albumin nanoparticles provide versatile solutions with promising advancements for treating brain tumors, neuroinflammatory disorders, and neurodegenerative diseases." (PMID 41445782, 2025). "However, the increased uptake of albumin and the overexpression of its transporters in brain tumor cells is well established, providing a compelling rationale for the advantages of a carrier system that utilizes albumin." (PMID 34141613, 2021). "Additionally, albumin has been shown to accumulate in high quantities within brain tumors due to the enhanced permeability and retention (EPR) effect." (PMID 34141613, 2021). "We thus reasoned that it might be worthwile to use synthetic B1R agonists to facilitate local entry of albumin-bound drugs given that the bound fraction will probably be released into brain tumors in order to maintain equilibrium." (PMID 22629405, 2012). "Moreover, as albumin-based nanoparticles offer a potential route for delivering drugs to the central nervous system (CNS), then it is of great importance to explore their use in treating neurodegenerative diseases and brain tumors." (PMID 39458651, 2024). "Also, albumin-based delivery systems have the ability to avoid the efflux mechanisms of the drug, determining an improved absorption of albumin-based nanoparticles into brain tumors." (PMID 37836018, 2023). "However, a prospective study is needed to determine whether albumin supply and intensive respiratory tract management can improve the prognosis of patients underwent craniotomy due to brain tumor." (PMID 34996896, 2022). "However, it is hard to foresee changes in blood brain barrier that might contribute to oedema during elective brain tumour resection, so control of oncotic pressure with albumin for these types of patients is controversial." (PMID 26425342, 2015). "The ATCC tumour cell inoculated animals only grew one tumour in either model of metastatic brain tumour induction, which was not sufficient to cause a significant difference in albumin immunoreactivity from vehicle level and thus did not increase the permeability of the BBB." (PMID 23374226, 2013). "The albumin drug delivery nanosystems mentioned in this paper have improved properties and can overcome the BBB to target brain tumors." (PMID 37836018, 2023). "Corem-Salkmon, in the frame of novel approach to deliver drugs directly into brain tumours, presented the application of biodegradable magnetic nanoparticles (NPs) with MTX, conjugated with the human serum albumin (HSA)." (PMID 32423175, 2020).
brain tumor (continued). "In patients suffering from primary brain tumors, CSF APRIL levels correlated to CSF cell number, CSF protein levels, and albumin quotient." (PMID 31615554, 2019). "Clinical trials have confirmed that FUS enables safe and transient BBB/BTB opening in localized brain regions, significantly increasing the concentrations of systemically administered drugs, such as trastuzumab, carboplatin, TMZ, liposomal DOX, and albumin-bound PTX, within brain tumors." (PMID 40806198, 2025).
cerebral edema (26 papers, 2008 to 2025). "The elevated mortality in the 4% albumin group was potentially associated with an increase in cerebral edema and elevated ICP." (PMID 40944047, 2025). "This indicates that maintaining serum albumin levels at ≥ 32 g/L may enable effective plasma expansion with smaller infusion volumes, enhancing hemodynamic stability while minimizing the risk of cerebral edema." (PMID 39336939, 2024). "Additionally, pregnancy-associated factors such as decreased plasma osmolality and albumin concentration, increased blood volume and cardiac output, and sodium and free water retention can predispose women to cerebral edema, potentially increasing intracranial pressure and causing papilledema." (PMID 40687716, 2025). "In the present study, we put albumin in the dialysate to create oncotic pressure for resolving brain edema." (PMID 40332503, 2025). "Experimental studies in animals have demonstrated that albumin can reduce brain edema and enhance systemic microcirculation and hemodynamics." (PMID 39336939, 2024). "In these situations, it is critical to preserve euvolemia by employing isotonic normal saline rather than hypotonic solutions, such as lactated Ringer’s or 4–5% albumin, as the latter can exacerbate cerebral edema." (PMID 39336939, 2024). "Maintaining normal serum albumin levels in normovolemic fluid management offers potential benefits such as hemodynamic stability and reduced cerebral edema." (PMID 39336939, 2024). "In our study, lower albumin and cerebral ultrasound signs of cerebral oedema correlate with lower peripapillary nerve fibre layer thickness." (PMID 33141256, 2021). "It is believed that extravasation of serum albumin after BBB breakdown activates the transforming growth factor beta-signalling pathway, and that this phenomenon can cause cerebral oedema and hyperperfusion." (PMID 30105409, 2019). "The spontaneous reduction in arterial pressure in combination with an active treatment with antihypertensive drugs and treatment with albumin should counteract the development of brain edema in the cranial opening." (PMID 28725211, 2017). "A study in rats showed that the use of albumin resulted in less brain edema after a head trauma than the use of saline in corresponding plasma-expanding doses." (PMID 28725211, 2017). "Apgar scores were higher, the frequency of cerebral edema lower and hospital stay shorter after hyperoncotic albumin administration in newborns with asphyxia and brain edema." (PMID 18318896, 2008). "In a cohort study of 10 patients with elevated intracranial pressure and brain edema, infusion of 2 g/kg 25% albumin over 60 min produced a significant and long-lasting (≥ 9 h) decline in intracerebral pressure." (PMID 18318896, 2008). "In a non-randomized trial of 22 patients with putaminal hemorrhage, 50 to 100 ml/day of 25% albumin with concomitant furosemide significantly reduced brain edema as assessed by computed tomography." (PMID 18318896, 2008). "Finally, albumin stabilizes endothelial barrier function, maintains blood–brain barrier integrity, and reduces post-reperfusion vascular leakage and cerebral edema." (PMID 40607035, 2025). "Experimental studies and clinical trials have shown that albumin can reduce cerebral edema." (PMID 39336939, 2024). "Some studies indicate that albumin may mitigate cerebral edema and stabilize hemodynamics, while others, such as the SAFE-TBI study, have reported increased mortality associated with its use, potentially due to the exacerbation of ICP." (PMID 39336939, 2024). "Nevertheless, the increase in serum SP levels we observed, in conjunction with the increased barrier permeability and vasogenic edema seen with albumin IHC and MRI, support a potential role for SP in the genesis of cerebral edema and development of elevated ICP in this model." (PMID 31338013, 2019).
cerebral edema (continued). "Apart from the absorbing effect of the increase in plasma oncotic pressure, which might reduce brain edema, albumin has a plasma-expanding effect, preventing hypovolemia, and thereby improving microcirculation in the penumbra zone." (PMID 28725211, 2017). "Experimental studies of cerebral edema have found that neutral and positively charged molecules can flow into ventricular CSF but molecules that are negatively charged at physiological pH, such as albumin and fluorescein isothiocyanate, flow to the subarachnoid CSF." (PMID 40494618, 2025). "Therefore, low albumin levels may further increase vascular permeability and promote cerebral edema." (PMID 40535050, 2025). "This correlated with the observed area of albumin staining, implicating SP and in the genesis of BBB breakdown and the development of cerebral edema." (PMID 24818961, 2014). "NT-proBNP may exacerbate cerebral edema by increasing microvascular permeability through its active product BNP, promoting albumin extravasation, and inhibiting interstitial fluid reabsorption." (PMID 40786638, 2025). "This characteristic allows albumin to maintain intravascular volume more effectively, which is critical in patients with TBI, in which adequate cerebral perfusion and the prevention of cerebral edema are paramount." (PMID 39336939, 2024).